KRAS (KRas proto-oncogene, GTPase)
Diseases named in the same sentence as KRAS in open-access papers (continued):
Sharing a sentence is not in itself a finding about the gene and the disease.
tumor (continued). "In addition, recent findings suggest that administration of an anti-EGFR monoclonal antibody in combination with a regimen containing oxaliplatin to patients with a KRAS mutant tumor might significantly reduce progression free survival." (PMID 22216189, 2011). "Indeed, tumor promoter hypermethylation of RASSF1A occurs in approximately 20% of CRC, and it seems to exist a mutually exclusive relationship with the presence of KRAS mutations." (PMID 20098741, 2010). "As KRAS mutation status has been shown to be a predictor of tumor response to anti-EGFR treatment, the EVEREST trial sought to determine whether dose escalation would also be able to induce a response in patients with KRAS mutations." (PMID 20680104, 2010). "To further exclude the possibility of pathological misclassification of endometrioid, clear cell or LGS tumours in the mutation-negative cases, we also tested for mutations commonly associated with these subtypes in KRAS (exon 2), BRAF (exon 15), CTNNB1 (exon 3), and PIK3CA (exons 10 and 21)." (PMID 20229506, 2010). "Patients with KRAS-mutant tumours treated with cetuximab in any combination had lower PFS compared with those with KRASWT tumours, results that extend those reported in recent clinical trials and suggest that KRAS mutation may bypass aberrant EGFR signalling." (PMID 19603024, 2009). "No KRAS mutation was found in the 12 patients with a complete or partial tumor response." (PMID 19386128, 2009). "Whole sections could not be evaluated as positive for KRAS mutations, while samples enriched in tumor cells were mutant (2 Gly12Asp, 1 Gly12Val)." (PMID 19888477, 2009). "Testing for tumor specific mutations on routine formalin-fixed paraffin-embedded (FFPE) tissues may predict response to treatment in Medical Oncology and has already entered diagnostics, with KRAS mutation assessment as a paradigm." (PMID 19888477, 2009). "Restricting analysis to the 92 patients who received cetuximab combinations as salvage therapy, none of the 32 patients with a KRAS-mutant tumour responded to treatment, whereas objective responses occurred in 14 of 60 (23%) patients whose tumors harboured only WT KRAS alleles (P=0.002)." (PMID 19603024, 2009). "Tumor FFPE-DNA from 135 diagnostic and 75 low-quality control samples was obtained upon macrodissection, tested for fragmentation and assessed for KRAS mutations with dideoxy-sequencing and with two Q-PCR methods (Taqman-minor-groove-binder [TMGB] probes and DxS-KRAS-IVD)." (PMID 19888477, 2009). "However, it is now clearly demonstrated that patients with a tumor KRAS mutation are resistant to anti-EGFR antibodies and do not benefit from this targeted therapy." (PMID 19785749, 2009). "The report on KRAS status in patients with metastatic CRC receiving epidermal growth factor receptor (EGFR) targeted antibody treatment has led to a change in National Comprehensive Cancer Network guideline that recommends only patients with wild-type KRAS tumor should receive this treatment." (PMID 19236713, 2009). "A recent report found that all KRAS mutations did not exert an equal effect on tumor cells." (PMID 19826477, 2009). "While there was a trend for an increased KRAS mutation frequency in nonresponder patients (12 mutations out of 23, 52%) as compared to responder patients (2 out of 9, 22%), authentic tumor response or long-term disease stabilization was found in KRAS mutated patients." (PMID 18544172, 2008). "None of the nine tumours with KRAS mutations responded to EGFR-TKIs." (PMID 17325698, 2007).
tumor (continued). "In conclusion, increasing evidence indicates that YAP is a major tumor-promoting transcription factor in PDAC and plays a significant role in circumventing KRAS function in the basal-like/squamous subtype of the disease." (PMID 41484057, 2026). "Molecular profiling revealed concurrent KRAS and CDK4 amplifications, providing a plausible mechanistic basis for the tumor's high proliferative index and aggressive behavior, and underscoring the biological heterogeneity underlying this rare presentation." (PMID 42222377, 2026). "The microtubule agent dolastatin 10 and the Class I HDAC inhibitor largazole suppress the oncogenic KRAS and HIF pathways, inducing tumor regression." (PMID 41362725, 2026). "Li's research team found that BNBZ induces metabolic reprogramming in KRAS-mutant CRC cells by inhibiting glycolytic flux, thereby suppressing the tumor cell growth." (PMID 41362725, 2026). "KRAS inhibitors can also remodel the TME, leading to the formation of pro-inflammatory TME, and resulting in the remodeling of the tumor immune microenvironment in KRAS-mutant cancers." (PMID 41362725, 2026). "The isoform-specific dysregulation of HIFs underscores divergent hypoxic pathway activation under mutant KRAS conditions, with elevated HIF-1α/β promoting tumor invasion and metastasis in PNETs." (PMID 41531732, 2026). "We found that MYC, E2F1, and EIF4E are all positively correlated with PRMT5 and KRAS with an R-value > 0.70 and a p-value < 0.01 in CRC patient tumor samples." (PMID 40864819, 2025). "Mechanistically, KDM7B upregulated the expression of PD-L1, KRAS, BRAF, and c-Myc and promoted immune escape and tumor progression by increasing the levels of H3K4me3 and H3K27ac and decreasing the level of H3K9me2." (PMID 40699666, 2025). "In preclinical models, co-treatment with the KRAS^G12D^ inhibitor MRTX1133 and SBRT significantly improved local tumor control and survival, suggesting clinical potential for combination approaches." (PMID 40725389, 2025). "In a recent study, Hu’s team found that KRAS can upregulate CD47, an antiphagocytic signal exploited by tumor cells, through the PI3K/STAT3 pathway to evade innate immune surveillance." (PMID 40282985, 2025). "In KRAS-mutant patients, RASON expression positively correlated with tumor stage and negatively correlated with macrophage infiltration in KRAS-mutant patients." (PMID 40128846, 2025). "Further, tumor tissue sectionsfrom the combination group showed reduced p-ERK and p-S6 expressions suggestingsuppression of KRAS mediated cell growth signaling." (PMID 41394580, 2025). "Hematoxylin and eosin sections were dissected into multiple, spatially distinct regions within each tumor and directly Sanger sequenced for the relevant region of BRAF and either KRAS or NRAS, as appropriate." (PMID 39751654, 2025). "From this perspective, KRAS-and EGFR-mutant tumors obviously diverge at multiple points in anti-tumor response, leading to distinct immune microenvironment phenotypes." (PMID 40809430, 2025). "Together, these findings establish SNX10 as a novel candidate tumor suppressor in PDAC, potentially antagonizing KRAS oncogenic function." (PMID 40810725, 2025).
tumor (continued). "Here, we address this hurdle by utilizing a nucleic acid-based therapeutic strategy delivered via extracellular vesicles (EVs) to simultaneously inhibit KRAS mutants and activate the RIG-I pathway, aiming to enhance anti-tumor immunity." (PMID 40585984, 2025). "BN1 effectively suppressed KRAS expression, thereby downregulating the MEK-ERK pathway and PD-L1 expression in tumor cells." (PMID 40885393, 2025). "In KRAS-driven lung adenocarcinoma, ISR promotes tumor growth and survival by enabling adaptation to hostile tumor microenvironments characterized by nutrient deprivation, hypoxia, and metabolic stress." (PMID 40870005, 2025). "Genetic alterations in oncogenic drivers such as EGFR, ALK, KRAS, BRAF, MET and others can modify immunogenicity and impact the tumor microenvironment (TME)." (PMID 40809430, 2025). "In addition, it was shown that KRAS-mutated cancer cells induce platelet aggregation, a phenomenon called TCIPA (tumor cell-induced platelet aggregation) that is associated with metastasis formation and might be an emerging therapeutic target in cancer therapy." (PMID 40427186, 2025). "Our study underscores the complexity of CRC and the pivotal role of KRAS, BRAF, and PIK3CA variations in tumor progression and outcomes in Iraq's Kurdistan Region, highlighting the importance of molecular profiling in clinical care." (PMID 40949797, 2025). "The nuclear enrichment of SOD1 is crucial for the proliferation of NSCLC cells, a fact corroborated by SOD1 inducible knockout studies in KRAS‐driven NSCLC mouse models, which significantly diminished the tumor burden in both in vivo and in vitro settings." (PMID 41498040, 2025). "The RAS family of small GTPases (including HRAS, KRAS, and NRAS) plays pivotal roles in tumor progression." (PMID 40919428, 2025). "Specifically, tumor burden decreased with increasing drug concentrations for bortezomib and YM155 in both WT and KRAS-mutant BEST." (PMID 41008802, 2025). "Oncogenic KRAS also reroutes Gln through a non‐canonical pathway involving GOT1 and MDH1 to sustain redox balance and fuel tumor growth." (PMID 40641572, 2025). "In the GSE19826 dataset, the tumor group’s expression levels of AKR1C2 and KRAS declined compared to the normal group; however, HCAR1 expression levels increased." (PMID 41050072, 2025). "For instance, EVs’ release results in increased tumor invasiveness by transferring tumor promoters such as mutant KRAS, Epidermal Growth Factor Receptor (EGFR) and integrins to tumor cells with wild-type KRAS." (PMID 41515889, 2025). "It was reported that the adoptive transfer of mutant KRAS-G12D-specific, HLA-C*08:02-restricted TILs (CD8+ T-cells) achieved durable tumor regressions in one patient with mCRC." (PMID 40361439, 2025). "A study on an animal model revealed that the KRAS-dependent signaling pathway is essential for the development of GBM in mice, and its inhibition results in tumor cell apoptosis." (PMID 40428422, 2025). "This regulatory axis is governed upstream by the KRAS/PI3K signaling pathway, ultimately enhancing mitochondrial OXPHOS and thereby promoting tumor invasion and migration." (PMID 40936169, 2025). "In NSCLC, oncogenic KRAS was found to stabilize the ERK3 protein and enhance phosphorylation at Ser‐189 across all tumour stages." (PMID 39348153, 2025).
tumor (continued). "In preclinical studies using mouse models, sotorasib, in addition to directly inhibiting KRAS, has been found to inhibit the phosphorylation of ERK (extracellular signal-regulated kinase), leading to complete tumor regression in KRASG12C-mutant cancers." (PMID 41309533, 2025). "In PDAC, mutant KRAS is sustained with a GTP‐binding active form, which acts as a driving factor to activate the tumour‐promoting signalling pathways like PI3K‐AKT, MAPK/ERK, and PLC‐NF‐kB pathways." (PMID 39843398, 2025). "Since MYC and KRAS-mediated signaling is frequently deregulated in HGSOC, we generated a tumor model by oncogenic transformation of iFTSECs, which constitute the origin of HGSOC." (PMID 40550880, 2025). "In the TCGA-STAD dataset, AKR1C2 exhibited reduced expression in the tumor group; conversely, HCAR1, KRAS, and PHKG2 showed increased expression in the tumor group." (PMID 41050072, 2025). "In KRAS‐mutant NSCLC, the ubiquitination network sustains tumour metabolic reprogramming through multiple mechanisms." (PMID 40313038, 2025). "Oncogenic KRAS plays a pivotal role in immune evasion by driving the upregulation of key immune checkpoint ligands, notably PD-L1 and CD47, on the surface of tumor cells." (PMID 41020848, 2025). "These in vivo results along with in vitro results validate our mechanistic findings and demonstrate that anlotinib combined with KRAS-G12Ci effectively overcomes resistance through modulation of the c-Myc/ORC2 axis, resulting in significant tumor suppression." (PMID 40316534, 2025). "Furthermore, KRAS mutations alone did not result in tumor formation, regardless of DSS treatment." (PMID 41285904, 2025). "Coactivation of KRAS and MYC enhances the secretion of tumor-derived CCL9 and IL-23, driving stromal reprogramming, promoting angiogenesis, and excluding tumor-infiltrating T, B, and NK cells." (PMID 40813760, 2025). "These proteins are shown to interact with both PRMT5 and KRAS in STRING, are overexpressed in CRC tumor samples, and show positive gene expression correlations with PRMT5 and KRAS in patient data." (PMID 40864819, 2025). "In contrast, both CDKN2A, a gene with tumor suppressive potential in both T-ALL and B-ALL, as well as KRAS, a B-ALL driver gene, were upregulated (Fig. SF5A)." (PMID 41282185, 2025). "This reduction led to increased expression of KRAS and downstream effectors ERK1/2 and BRAF, enhancing the viability of tumor cells and promoting metastasis." (PMID 41416095, 2025). "Clinically, KRAS-mutant tumors with STK11/KEAP1 inactivation are known to be less responsive to immune checkpoint inhibitors and often exhibit a “cold” tumor immune microenvironment (low PD-L1, Programmed Death-Ligand 1, with low T-cell infiltration)." (PMID 40723270, 2025). "In KRAS-mutant xenografts, SIAIS562055 displayed promising antitumor potency as a monotherapy and enhanced ERK inhibition and tumor regression when combined with KRAS inhibitors, overcoming acquired resistance." (PMID 39437162, 2025). "This process is catalyzed by the enzyme farnesyltransferase and is essential for KRAS signaling through downstream pathways such as MAPK and PI3K/AKT, promoting tumor cell proliferation and survival." (PMID 40862711, 2025). "In this context, miRNAs inhibiting expression of PTEN (miR-425 and miR-148a) should be considered as oncomirs, and those inhibiting KRAS, EGFR, PIK3CA, TGFBR1, and SMAD2 (let-7g, miR-150, miR-128, miR-139, miR-148a, miR-148b) as tumor suppressors." (PMID 40868120, 2025). "KRAS is a proto-oncogene that activates the MAPK signaling pathway, promoting uncontrolled cell proliferation and tumor progression." (PMID 40507920, 2025).
tumor (continued). "Studies on human tumoroids showed divergent results, demonstrating either a tumor‐suppressive response and minimal changes in EMT marker gene expression or KRAS‐dependent resistance to TGF‐β treatment through downregulation of the pro‐apoptotic protein BIM." (PMID 40066744, 2025). "In contrast, KRAS-mutant CRC tumors were enriched with proteins like IGFBP2 and KRT18, indicative of a more aggressive, tumor-promoting molecular phenotype." (PMID 41294676, 2025). "ARS-1620 binds specifically to KRAS G12C mutants, and in vivo studies have shown that ARS-1620 can significantly inhibit tumor growth and regression." (PMID 40597785, 2025). "In contrast, we demonstrated that a single injection of Gel@Cmab/PCZ induced sustained tumor growth inhibition and achieved 91% tumor growth inhibition at markedly lower doses than cetuximab (i.v.)in a CRC PDX model with KRAS mutant." (PMID 39560161, 2025). "None of the analyzed variables (age, sex, histology, stage, EGFR, KRAS and PD-L1 status) were found to display a significant correlation with IDO-1 positivity in tumor and immune cells." (PMID 40475772, 2025). "While exosomes enhance immune activation through antigen presentation and can be engineered to deliver siRNAs targeting oncogenes such as KRAS and MYC, they also contribute to reprogramming the tumor microenvironment to counteract immunosuppression." (PMID 40149276, 2025). "Preclinical in vitro studies reveal that inhibiting KRAS sensitizes PDAC cells to NK cell-mediated attacks, improving anti-tumor NK cell function." (PMID 39859231, 2025). "Additionally, KRAS G12D mutation regulates the transcription of key metabolic enzymes such as glutamate dehydrogenase (GLUD1) and aspartate aminotransferase (GOT1), enabling tumor cells to meet carbon and nitrogen demands for rapid proliferation and macromolecular synthesis." (PMID 40427667, 2025). "The top row shows key drivers‐KRAS, c‐Myc and HIF‐1a‐alongside gut and tumor microbiota, all converging on glutamine metabolism in PDAC." (PMID 40641572, 2025). "patient age, CEA levels, lymphocyte count, albumin, NLR, SII, PNI, tumor distance from the anal verge, tumor length, tumor involvement of the bowel circumference, cT stage, cN stage, TRG grade, KRAS status, and MSI status were correlated with survival." (PMID 40444087, 2025). "In this study, we achieved potentiation of HLA-A2/KRAS G12V-CD3 BiTE, via modification of a tumor-penetrating peptide that induce T-cell responses." (PMID 41472736, 2025). "This study presents a novel chimeric siRNA that simultaneously targets KRAS and MYC, enhancing cancer inhibition in vitro and reducing tumor burden in vivo." (PMID 40762837, 2025). "The selected biomarkers (EGFR, ALK, KRAS, and PDCD1), demonstrated significantly higher expression in NSCLC tumor tissues compared to adjacent normal tissues (p < 0.01)." (PMID 40927719, 2025). "In five patients, KRAS mutation status could not be assessed due to low ctDNA/tumor fractions." (PMID 41044171, 2025). "Emerging strategies combining KRAS inhibitors and TME‐editing approaches offer potential to dismantle tumor‐ecosystem crosstalk and advance precision oncology." (PMID 40485603, 2025).